ANXA8L1 (annexin A8 like 1)
Synonyms: ANXA8L2; bA301J7.3; bA145E20.2
Tractability: Antibody: its Gene Ontology location is reachable by antibodies, with medium confidence. PROTAC: ubiquitination databases record sites on it.
Gene: Protein-coding gene on chromosome 10 (46,375,587 to 46,391,784, forward strand). Ensembl gene ENSG00000264230.
Subcellular location (Human Protein Atlas): Vesicles
Gene Ontology:
Molecular function: calcium-dependent phospholipid binding; phosphatidylserine binding; calcium ion binding
Biological process: endosomal transport; endosome organization
Cellular component: sarcolemma; vesicle membrane
Genetic constraint (gnomAD): Loss-of-function variants: 8 observed, 7.18 expected, observed/expected ratio (o/e) 1.11, 90% interval 0.65 to 1.81. That is too few expected variants to judge how well the gene tolerates losing a copy. Missense variants: 41 observed, 74.35 expected, observed/expected ratio (o/e) 0.55, 90% interval 0.43 to 0.72. Synonymous variants: 14 observed, 27.64 expected, observed/expected ratio (o/e) 0.51, 90% interval 0.33 to 0.79.
Homologues: Orthologues: rabbit ANXA8 (93% identical), rat Anxa8 (93% identical), mouse Anxa8 (92% identical), dog ANXA8L1 (88% identical), Drosophila melanogaster AnxB9 (48% identical), Drosophila melanogaster AnxB11 (43% identical), zebrafish anxa13 (42% identical), zebrafish anxa13l (40% identical), zebrafish anxa14 (27% identical). Paralogues in human: ANXA8 (99% identical), ANXA5 (55% identical), ANXA4 (54% identical), ANXA11 (52% identical), ANXA6 (51% identical), ANXA7 (49% identical), ANXA3 (49% identical), ANXA13 (46% identical), ANXA2 (45% identical), ANXA1 (43% identical), ANXA10 (38% identical), ANXA9 (35% identical).
Diseases named in the same sentence as ANXA8L1 in open-access papers:
ANXA8L1 is named in the same sentence as 16 diseases in open-access papers, as found by Europe PMC text mining. Sharing a sentence is not in itself a finding about the gene and the disease. The quoted sentences say what the papers report.
bladder urothelial carcinoma (1 paper, 2022). "ANXA8L1 (kidney renal papillary cell carcinoma) and CYP4B1 (lung adenocarcinoma and bladder urothelial carcinoma) were highly expressed at the early stage of these cancers, but PSMF1 was highly expressed in stage III stomach adenocarcinoma." (PMID 35807355, 2022).
breast carcinoma (1 paper, 2024). "The top four upregulated differentially expressed genes (DEGs), SAA2, UBE2C, CEMIP and ANXA8L1, have been associated with increased inflammation, cancer progression, metastatic potential and overall poor survival outcomes of various cancers including breast cancer." (PMID 39768151, 2024).
cervical squamous cell carcinoma (1 paper, 2022). A squamous cell carcinoma arising from the cervical epithelium. "High expression of ANXA8L1 was detected to be associated with poor prognosis in cervical squamous cell carcinoma and endocervical adenocarcinoma (CESC), but there were few studies on the relationship between ANXA8L1 and lung cancer." (PMID 35807355, 2022).
cholangiocarcinoma (1 paper, 2022). A carcinoma that arises from the intrahepatic biliary tree (intrahepatic cholangiocarcinoma) or from the junction, or adjacent to the junction, of the right and left hepatic ducts (hilar cholangiocarcinoma). "The results indicated that ANXA8L1 (cholangiocarcinoma), PSMF1 (stomach adenocarcinoma) and TNS4 (head and neck squamous cell carcinoma, lung squamous cell carcinoma, rectum adenocarcinoma, stomach adenocarcinoma) were highly expressed in these cancers." (PMID 35807355, 2022).
COVID-19 (1 paper, 2020). A disease caused by infection with severe acute respiratory syndrome coronavirus 2. "ECM-associated proteins include several anticoagulant proteins (e.g. the annexin family members ANXA3, ANXA4, ANXA5, and ANXA8L1) of ECM-affiliated proteins were markedly diminished, which is consistent with the results indicating coagulation dysfunction in the COVID-19 patients." (PMID 33060566, 2020).
lung adenocarcinoma (1 paper, 2022). A carcinoma that arises from the lung and is characterized by the presence of malignant glandular epithelial cells. "Furthermore, ANXA8L1 (kidney renal papillary cell carcinoma), CYP4B1 (lung adenocarcinoma) and TNS4 (stomach adenocarcinoma) showed a significant relation with survival in these cancers." (PMID 35807355, 2022).
pemphigus vulgaris (1 paper, 2022). Pemphigus is a group of chronic autoimmune skin diseases characterized by blister formations on the outer layer of the skin and the mucous membranes. "ANXA8L1 (annexin A8 like 1) encoded one of the top 10 antigens identified by the majority of serological tests for pemphigus vulgaris patients." (PMID 35807355, 2022).
ANXA8L1 also shares sentences with these, for which no sentence is quoted: cancer (3 papers); endocervical adenocarcinoma (1); Esotropia (1); head and neck squamous cell carcinoma (1); lung carcinoma (1); lung squamous cell carcinoma (1); Obesity (1); rectum adenocarcinoma (1); stomach adenocarcinoma (1).